ITGB1 (integrin subunit beta 1)
Diseases named in the same sentence as ITGB1 in open-access papers (continued):
Sharing a sentence is not in itself a finding about the gene and the disease.
colorectal cancer (27 papers, 2018 to 2025). A primary or metastatic malignant neoplasm that affects the colon or rectum. "While overexpression of ITGAV was linked to progression and perineural invasion in colorectal cancer, ITGB1 expression in tumors was associated with shortened overall survival and shortened disease-free survival in a large cohort of patients with colorectal tumor." (PMID 30473751, 2018). "Similarly, high ITGB1 expression associates with poor patient prognosis and independently correlates with shortened overall survival and shortened disease-free survival in people with colorectal cancer." (PMID 33777753, 2021). "ITGB1 promotes cell proliferation and migration in colorectal cancer and sensitizes HCC cells to sorafenib treatment upon its ablation." (PMID 41392988, 2025). "Up-regulation of ITGB1 can stimulate the proliferation, invasion and migration capacities of colorectal cancer cells." (PMID 33591944, 2021). "Accumulating evidence illustrated that ITGB1 sustains cell proliferation through the upregulation of cyclin D1 in colorectal cancer cells and satellite cells." (PMID 34977001, 2021). "RNAi-mediated knockdown of ITGB1 in human colorectal cancer cells significantly reduced the proliferation and invasion and resulted in slower tumor growth rates and smaller tumor volumes compared to control transfections in xenograft mouse models." (PMID 30473751, 2018). "A previous study showed that altered ITGB1 expression had a significant correlation with lymph node metastasis and depth of invasion in colorectal cancer." (PMID 30595764, 2018). "Notably, conserved overexpression of JUN/FOS (AP-1 complex) and ITGB1 was observed across all three cancer types and colorectal cancer, underscoring their roles as shared molecular drivers." (PMID 40725477, 2025). "For example, in cancer cells, ITGB1 can bind to EpCAM and regulate cell adhesion; The high expression of ITGB1 may be related to the poor prognosis of colorectal cancer and can lead to the migration and invasion of colorectal cancer cells." (PMID 37007126, 2023). "The reduction of ITGB1 in response to the MYCi in the normal intestinal HIEC cells is consistent with the fact that ITGB1 contains the cognate CACGTG E-box in its promoter while previous experiments have shown that MYC only plays a minor role on the ITGB1 promoter in colorectal cancer cells." (PMID 29401653, 2018). "The expression of ITGB1, the most highly expressed integrin, was significantly reduced in HCT116 and SW620 cells by ropivacaine, which suppressed colorectal cancer cell proliferation, migration, and invasion." (PMID 39258668, 2024). "This study showed that under the action of ropivacaine, the expression of ITGB1 in HCT116 and SW620 cells was significantly reduced, and ropivacaine can inhibit the proliferation, migration, and invasion of colorectal cancer cells." (PMID 33345684, 2021). "This study showed that under the action of ropivacaine, the expression of β1 integrin (ITGB1) in HCT116 and subcutaneous colorectal cancer xenograft tumor model (SW620) cells was significantly reduced, and ropivacaine can inhibit the proliferation, migration, and invasion of colorectal cancer cells." (PMID 39310634, 2024). "The TCGA data analysis showed that the downstream DCBLD2 gene was enriched in the focal adhesion pathway in colorectal cancer, and DCBLD2 and the key signal factor ITGB1 of the focal adhesion pathway show a significant positive correlation in the mRNA expression level." (PMID 34095137, 2021).
hepatocellular carcinoma (27 papers, 2007 to 2026). A malignant tumor that arises from hepatocytes. "In this study, we suggest an alternative methodological framework for designing potent siRNAs targeting genes implicated in hepatocellular carcinoma, implementing RNA interference mediated by synthetic small interfering RNAs (siRNAs) against mRNAs of ITGB1 and CD47 genes." (PMID 41596257, 2026). "In hepatocellular carcinoma, circPABPC1 directly links integrin subunit beta 1 (ITGB1) to the 26S proteasome for degradation in a ubiquitination-independent manner." (PMID 39966624, 2025). "In a xenograft model of TNBC, RGD peptide-directed siRNA-loaded nanoparticles targeting ITGB3 have significant therapeutic benefits, and lipid nanoparticles with ITGAV and ITGB1-targeted siRNA suppress hepatocellular cancer in vivo." (PMID 38279122, 2024). "In hepatocellular carcinoma, ITGB1 regulated the cell cycle process via the PXN/YWHAZ/AKT pathway, promoting hepatocellular carcinoma progression." (PMID 38183097, 2024). "It has been previously reported that miR-134, through targeting ITGB1, suppressed metastasis of hepatocellular carcinoma." (PMID 35804897, 2022). "In this study, we better clarified the oncogenic role and crucial molecular mechanism of ITGB1 on HCC progression by utilizing the liver hepatocellular carcinoma (LIHC) dataset retrieved from The Cancer Genome Atlas (TCGA) and functional enrichment analysis." (PMID 34977001, 2021). "ITGB1 is closely related to PI3K/AKT signaling pathway, and has been widely studied in tumors, including hepatocellular carcinoma and cervical cancer." (PMID 35570248, 2022). "While ITGB1 and CD47 are implicated in hepatocellular carcinoma, therapeutic efficacy in HCC models was not evaluated here and will require future validation in hepatocyte-derived and in vivo systems." (PMID 41596257, 2026). "To confirm this universal role of ITGB1 in nHEV entry, we transfected other hepatoma and non-hepatoma cell lines, such as Huh-7, HepG2/C3A, lung A549, and intestinal Caco-2 cells with small interfering RNA (siRNA) targeting ITGB1 (siITGB1) or non-targeting siRNA (siNT) 48 h prior to HEV inoculation." (PMID 40571699, 2025). "For example, microRNA-3653 targeting ITGB1 restrains the growth and metastasis in hepatocellular carcinoma; microRNA-183-5p inhibits cervical cancer aggressiveness through targeting ITGB1; lncRNA TUG1/miR-29c axis influences cell proliferation, invasion, and migration in PC by regulating ITGB1." (PMID 31693728, 2019). "Integrin β1 (ITGB1), which acts as an extracellular matrix (ECM) receptor, has gained increasing attention as a therapeutic target for the treatment of hepatocellular carcinoma (HCC)." (PMID 34977001, 2021).
prostate carcinoma (27 papers, 2006 to 2024). A carcinoma that arises from epithelial cells of the prostate gland. "ITGB1 was involved in cell adhesion and invasion of prostate cancer cells, but this gene may be associated with invasion of EOC." (PMID 30970615, 2019). "In prostate cancer (PC), ITGB1 controls the CAV1 expression, and METTL3 maintains ITGB1 levels at m6A levels, which contributes to the theory of ITGB1 concentration in transcriptional modifications." (PMID 38279122, 2024). "Although the role of integrins in cancer progression is controversial and likely tissue- and time-specific, in this study we show that ITGB1 has an expression pattern of a tumor suppressor gene in prostate cancer tissues." (PMID 35202085, 2022). "Overall, cell adhesion was uncovered as a major pathway controlled by miR-183 in prostate cancer, and ITGB1 was identified as a relevant mediator of this effect." (PMID 35202085, 2022). "ITGA3 gene knockdown significantly decreases head and neck cancer cell migration and invasion, whereas suppression of miR-223 microRNA synthesis, which enhances intracellular signal transmission from ITGA3/ITGB1, stimulates cell motility in prostate cancer." (PMID 34503200, 2021). "The HOXB13/HOXA11-AS axis also regulated integrin subunits (ITGAV and ITGB1) specific to prostate cancer bone metastasis." (PMID 33514011, 2021). "We also revealed that miR-223 acted as an antitumor miRNA through targeting ITGA3 and ITGB1 in prostate cancer." (PMID 29423074, 2018). "ITGB1 is a protein involved in extra-cellular matrix interactions and is also related to many tumor types, including prostate cancer." (PMID 16608523, 2006). "Overall, the results indicate that a negative regulation of ITGB1 by miR-183 may be operative in prostate cancer patient tissue, as well as in cell lines, and might contribute to prostate cancer biology." (PMID 35202085, 2022). "A recent study reported that METTL3 could stabilize ITGB1 mRNA via an m6A-HuR-dependent mechanism to promote bone metastasis in prostate cancer." (PMID 34277426, 2021). "In addition, radiation-induced upregulation of ITGB1 has been demonstrated in vitro and in vivo in prostate cancer cells, as well as upregulation of ITGA5 on colorectal tumor cells after X-ray irradiation." (PMID 34211843, 2021). "However, in addition to ERG and ITGA3/ITGB1 signaling, alternative target genes of miR-233 remain to be elucidated in prostate cancer." (PMID 34395419, 2021). "In good accordance, it has been shown that transmembranous shifting of the integrin subtype β1 (ITGB1) may contribute to metastatic progression of bladder cancer cells, and ITGB3 translocation has been associated with adhesive behaviour in prostate cancer cells." (PMID 29721158, 2018). "Studies have shown that in prostate cancer cells with decreased expression of IGF1R, the expression of ITGB1 is also significantly decreased." (PMID 38292328, 2024). "In the present study, miR-233 was predicted to bind with circGNG4, and miR-223 has been determined to inhibit prostate cancer progression by targeting ETS transcription factor ERG (ERG) and integrin subunit α 3 (ITGA3)/integrin subunit β 1 (ITGB1) signaling." (PMID 34395419, 2021). "In prostate cancer, miR-223 suppressed tumor cell proliferation, migration, and invasion by targeting ITGA3/ITGB1 (integrin subunit alpha 3/ integrin subunit beta 1) signaling." (PMID 27618431, 2016). "METTL3 also regulates integrin subunit beta 1 (ITGB1) expression, thereby affecting the binding of ITGB1 to collagen I. This disruption affects tumor cell migration and promotes bone metastasis in prostate cancer." (PMID 35571068, 2022). "The negative correlation between miR-183 and ITGB1 expression in prostate cancer cohorts supports their interaction in the clinical set." (PMID 35202085, 2022).
prostate carcinoma (continued). "We compared the expression levels of eight integrin subunits (ITGA2, ITGA5, ITGAV, ITGB1, ITGB3, ITGB4, ITGB5, and ITGB6), HOXB13, HOXA11-AS, CCL2, CXCL12, and IBSP in prostate cancer tissues that had metastasized to bone, lymph nodes, lungs, liver, and other organs." (PMID 33514011, 2021). "As we showed that ITGB1 is an upstream regulator of CAV1 expression and the two proteins are correlated in vitro, we asked if this correlation could be validated in a large clinical prostate cancer cohort." (PMID 29402961, 2018).
glioblastoma (20 papers, 2009 to 2025). The most malignant astrocytic tumor (WHO grade IV). "Among them, TNC+ and ITGB1+ EVs showed significantly higher levels innewly diagnosed and recurrent glioblastoma patients compared to HDand post-OP subjects." (PMID 40056466, 2025). "Previous study has indicated that ITGB1 immunostaining was heterogeneous in both intensity and frequency, and its distribution was patchy throughout the glioblastoma tumor sample with strongly positive immunostaining signal often close to the necrotic regions." (PMID 33014056, 2020). "We demonstrate that RNA isolated from pseudopodia of hGCs contains migration-specific transcripts including Cdc42, Cofilin-1, Ezrin, Ilk, Limk, STAT3, MMP2, and Itgb1, recently described as part of intracellular pathways related to glioblastoma migration." (PMID 30353164, 2019). "It is speculated that RELN may mediate cell–cell signaling, cell migration, or other related biological processes in glioblastoma cells by binding to its receptor ITGB1." (PMID 40149878, 2025). "Additionally, the expression level of ITGB1 in an orthotopic xenograft model of invasive glioblastoma is down-regulated." (PMID 38167011, 2024). "On the other hand, alterations of SGCG, HTR4, ITGB1, CPS1, PROS1 and INPP5A were detected predominantly in anaplastic astrocytoma, while alterations of PDE4D were present in both glioblastoma subtypes." (PMID 24358143, 2013). "Similarly, analysis of ITGB1 expression using the TIMER database showed overexpression in several cancers, including CHOL, esophageal carcinoma (ESCA), glioblastoma (GBM), KIRC, and LIHC." (PMID 40667648, 2025). "Our functional enrichment of genes in patient tumors revealed that low expression of RND1 in glioblastoma induces an overexpression of focal adhesion proteins like extracellular matrix proteins (COL1A1 and LAMB1); integrins (ITGA5 and ITGB1); actin-binding proteins (FLNA; ACTN1) and vinculin." (PMID 30333910, 2018). "However, ITGB1 was found to be nonspecificallyexpressed in glioblastoma tissue according to spatial transcriptomicanalyses, despite the high ITGB1+ EV counts in glioblastomapatients, which is also supported by the literature, suggesting that much of thisfraction is contributed by the TME." (PMID 40056466, 2025).
colon carcinoma (16 papers, 2010 to 2026). "ITGB1 expression was linked to immune cell infiltration in colon cancer, according to an investigation of immune infiltration in pan-cancer." (PMID 38402311, 2024). "Expression levels of Pcna, Ccnd1(CyclinD1), Bcl2, Itga2, Itgb1, Fak, Pik3r1, Akt1, Mtor and Myc were remarkably upregulated and Bax was downregulated in colonic tumors of mice treated with S. moorei." (PMID 39990665, 2025). "Ropivacaine regulates the function of colon cancer cells by targeting the expression of ITGB1 protein and affecting the activation of its downstream signaling pathways." (PMID 33345684, 2021). "Objective to investigate the effect of ropivacaine on the proliferation and migration of colon cancer cells by targeting ITGB1." (PMID 33345684, 2021). "Previous research has illustrated that ITGB1 plays an indispensable role in the survival and metastatic potential of lung, breast, and colon tumors." (PMID 34556089, 2021). "RT-PCR, Western blot and immunofluorescence verify the distribution and expression of the drug target ITGB1, and detect its downstream-related proteins to further prove that ropivacaine affects colon cancer cells by acting on ITGB1 protein." (PMID 33345684, 2021). "Integrins are involved in cell adhesion/movement, and Itgb1 has been shown to activate the RhoA-ROCK pathway in colon carcinoma cells." (PMID 25538140, 2014). "In this study, we investigated the effects of ropivacaine on the proliferation, migration and apoptosis of colon cancer cells, and further studied whether ropivacaine regulates the biological function of colon cancer cells through ITGB1." (PMID 33345684, 2021). "In addition, we confirmed for the first time that ropivacaine regulates the biological function of colon cancer cells through ITGB1." (PMID 33345684, 2021). "Ropivacaine could interact with ITGB1 protein, and inhibited the expression of ITGB1 protein in colon cancer cells, thereby affecting its downstream signaling pathway." (PMID 33345684, 2021). "However, whether ropivacaine inhibited cell proliferation and migration through ITGB1 expression in colon cancer cells remains unclear." (PMID 33345684, 2021).
cervical carcinoma (14 papers, 2015 to 2025). A carcinoma arising from either the exocervical squamous epithelium or the endocervical glandular epithelium. "On this basis, we considered whether KLF14 might be associated with ITGB1, thereby affecting the development of cervical cancer." (PMID 35570248, 2022). "Therefore, we considered that KLF14 might associate with ITGB1 to promote the apoptosis of cervical cancer cells, thereby inhibiting the development of cervical cancer." (PMID 35570248, 2022). "Recently, it was shown that KLF14 suppresses the cervical cancer progression by reduction of the cell proliferation and enhancement of the apoptosis through integrin β1 (ITGB1) via the PI3K/AKT signalling pathway." (PMID 36831624, 2023). "KLF14 inhibits the progression of cervical cancer by targeting ITGB1 via the PI3K/AKT signalling pathway." (PMID 36831624, 2023). "We used flow cytometry to demonstrate that KLF14 promoted apoptosis of cervical cancer cells, and in our mechanistic exploration, we found that it targets ITGB1 to regulate downstream PI3K/AKT signaling—thus promoting apoptosis." (PMID 38143751, 2023). "In summary, KLF14 inhibits the progression of cervical cancer by targeting ITGB1 via the PI3K/AKT signalling pathway." (PMID 35570248, 2022). "Flow cytometry confirmed that when ITGB1 was solely overexpressed (Lv-ITGB1), the apoptosis rate of cervical cancer SiHa cells was lower than that of the Lv-control (ITGB1) group, indicating that ITGB1 inhibits the apoptosis of cervical cancer cells." (PMID 35570248, 2022). "Mechanistically, ITGB1 expression was significantly downregulated in KLF14-overexpressing cervical cancer cells." (PMID 35570248, 2022). "Flow cytometry experiments confirmed that the apoptosis rate of SiHa cells decreased when ITGB1 was overexpressed, indicating that ITGB1 inhibited the apoptosis of cervical cancer cells." (PMID 35570248, 2022). "Third, to further prove the relationship between KLF14 and ITGB1 and their effects on cervical cancer, we conducted functional experiments." (PMID 35570248, 2022). "The effect of ITGB1 on cervical cancer cell apoptosis was reversed by KLF14, resulting in increased apoptosis." (PMID 35570248, 2022). "We also found that ITGB1 reversed the effect of KLF14 on cervical cancer cell apoptosis, resulting in decreased apoptosis." (PMID 35570248, 2022). "First, Western blotting was performed to verify that when KLF14 was overexpressed, ITGB1 expression was downregulated in cervical cancer SiHa and HeLa cells." (PMID 35570248, 2022). "This revealed that KLF14 could inhibit ITGB1 expression in cervical cancer cells at the protein level." (PMID 35570248, 2022). "In addition, the apoptosis rate of cervical cancer cells treated with Lv-KLF14 + Lv-ITGB1 was lower than that of cervical cancer cells treated with Lv-KLF14 + Lv-control (ITGB1)." (PMID 35570248, 2022). "Moreover, Flow cytometry was performed to verify the relationship between KLF14 and ITGB1 on the apoptosis of cervical cancer cells." (PMID 35570248, 2022). "We considered whether the effect of KLF14 targeting ITGB1 on the progression of cervical cancer was related to the PI3K/AKT signalling pathway." (PMID 35570248, 2022). "At the same time, we found that the effects of KLF14 and ITGB1 on apoptosis of cervical cancer cells could be mutually affected." (PMID 35570248, 2022). "This may provide evidence for our finding that ITGB1 inhibits apoptosis of cervical cancer cells confirmed by flow cytometry." (PMID 35570248, 2022). "Our study aimed to determine whether Krüppel-like factor 14 (KLF14) inhibits the proliferation and promotes the apoptosis of cervical cancer cells through integrin β1 (ITGB1)." (PMID 35570248, 2022). "Therefore, we believe that KLF14 and ITGB1 may be correlated and affect the development of cervical cancer through the PI3K/AKT signalling pathway." (PMID 35570248, 2022).